AGK (acylglycerol kinase)
Description:
Lipid kinase that can phosphorylate both monoacylglycerol and diacylglycerol to form lysophosphatidic acid (LPA) and phosphatidic acid (PA), respectively. Does not phosphorylate sphingosine. Phosphorylates ceramide (By similarity). Phosphorylates 1,2-dioleoylglycerol more rapidly than 2,3-dioleoylglycerol (By similarity). Independently of its lipid kinase activity, acts as a component of the TIM22 complex. The TIM22 complex mediates the import and insertion of multi-pass transmembrane proteins into the mitochondrial inner membrane by forming a twin-pore translocase that uses the membrane potential as the external driving force. In the TIM22 complex, required for the import of a subset of metabolite carriers into mitochondria, such as ANT1/SLC25A4 and SLC25A24, while it is not required for the import of TIMM23. Overexpression increases the formation and secretion of LPA, resulting in transactivation of EGFR and activation of the downstream MAPK signaling pathway, leading to increased cell growth.
Synonyms: MuLK; FLJ10842; CATC5; CTRCT38; MTDPS10
Tractability: Small molecule: a structure with a bound ligand is known. Antibody: UniProt places it where antibodies can reach, with high confidence. PROTAC: ubiquitination databases record sites on it; its protein half-life has been measured.
Target class: Enzyme; Transferase
Gene: Protein-coding gene on chromosome 7 (141,551,278 to 141,655,244, forward strand). Ensembl gene ENSG00000006530.
Subcellular location: Mitochondrion inner membrane; Mitochondrion intermembrane space
Subcellular location (Human Protein Atlas): Mitochondria; Vesicles
Pathways (Reactome):
Disease: Signaling by BRAF and RAF1 fusions
Metabolism: Glycerophospholipid biosynthesis
Gene Ontology:
Molecular function: acylglycerol kinase activity; ATP-dependent diacylglycerol kinase activity; protein binding; ceramide kinase activity; kinase activity; lipid kinase activity
Biological process: protein insertion into mitochondrial inner membrane; ceramide biosynthetic process; sphingosine biosynthetic process; glycerolipid metabolic process
Cellular component: mitochondrial inner membrane; mitochondrial intermembrane space; mitochondrial membrane; mitochondrion; TIM22 mitochondrial import inner membrane insertion complex; cytosol; mitochondrial outer membrane; plasma membrane; membrane
Genetic constraint (gnomAD): Loss-of-function variants: 24 observed, 36.75 expected, observed/expected ratio (o/e) 0.65, 90% interval 0.47 to 0.92. The upper end of that interval is the gene's LOEUF score, 0.92, which puts it in group 3 of 6, group 1 being the genes least tolerant of losing a copy. Missense variants: 303 observed, 358.38 expected, observed/expected ratio (o/e) 0.85, 90% interval 0.77 to 0.93. Synonymous variants: 135 observed, 132.84 expected, observed/expected ratio (o/e) 1.02, 90% interval 0.88 to 1.17.
Gene-disease validity (ClinGen):
ClinGen rates the evidence that AGK causes each of these diseases.
mitochondrial disease (autosomal recessive): Definitive.
Homologues: Orthologues: chimpanzee AGK (99% identical), macaque AGK (98% identical), guinea pig AGK (93% identical), dog AGK (92% identical), mouse Agk (91% identical), rat Agk (90% identical), pig AGK (88% identical), tropical clawed frog agk (67% identical), zebrafish agk (59% identical), rabbit AGK (55% identical), Drosophila melanogaster Mulk (25% identical), Caenorhabditis elegans F52C9.3 (23% identical). Paralogues in human: CERK (21% identical), CERKL (20% identical), SPHK1 (18% identical), SPHK2 (18% identical).
Diseases named in the same sentence as AGK in open-access papers:
AGK is named in the same sentence as 67 diseases in open-access papers, as found by Europe PMC text mining. Sharing a sentence is not in itself a finding about the gene and the disease. The quoted sentences say what the papers report.
Sengers syndrome (31 papers, 2013 to 2026). Congenital cataract - hypertrophic cardiomyopathy - mitochrondrial myopathy (CCM) is a mitochondrial disease characterized by cataracts, hypertrophic cardiomyopathy, muscle weakness and lactic acidosis after exercise. "In human, autosomal recessive mutations in AGK are associated with Sengers syndrome (10 cases with AGK mutants identified in 12 cases of Sengers syndrome), which was characterized by congenital cataracts, HCM, skeletal myopathy, and lactic acidosis." (PMID 40556660, 2025). "Our analysis successfully diagnosed Sengers syndrome in a patient by detecting a known pathogenic variant and a previously unreported large deletion involving the AGK gene in a segmental duplication." (PMID 39817524, 2025). "Here, we report the successful diagnosis of Sengers syndrome with a known pathogenic variant and a large deletion including the AGK gene within a segmental duplication by combining different genomic analysis approaches." (PMID 39817524, 2025). "Another example is the Sengers syndrome caused by mutations in the AGK gene encoding the mitochondrial enzyme acylglycerol kinase (AGK)." (PMID 40713843, 2025). "The gene responsible for Sengers syndrome is acylglycerol kinase (AGK), the loss of which results in a decreased adenine nucleotide translocator in the inner mitochondrial membrane." (PMID 39817524, 2025). "This study reports the successful diagnosis of Sengers syndrome using comprehensive genomic analysis, identifying both a known pathogenic AGK variant and a previously unreported large deletion in a segmental duplication region." (PMID 39817524, 2025). "Mutations in the gene encoding for acylglycerol kinase (AGK), which is also a part of the mitochondrial import machinery, cause Sengers syndrome, a rare autosomal recessive PMD." (PMID 38069070, 2023). "Sengers syndrome is an autosomal recessive disorder caused by mutations in the gene encoding acylglycerol kinase (AGK)." (PMID 36802007, 2023). "Sengers syndrome is a rare mitochondrial disease caused by AGK mutations and characterized by cataracts, hypertrophic cardiomyopathy, muscle weakness, lactic acidosis after exercise, and liver dysfunction." (PMID 35547757, 2022). "AGK mutation causes Sengers syndrome; one clinical case reported a patient with homozygous pathogenic variant c.979A>T; p.K327* exhibiting synthetic liver dysfunction." (PMID 35547757, 2022). "Sengers syndrome is characterized by congenital cataract, hypertrophic cardiomyopathy, mitochondrial myopathy, and lactic acidosis associated with mutations in AGK gene." (PMID 36253788, 2022). "Considered the family history and her clinical condition, Sengers Syndrome was suspected, and gene testing showed the same homozygous c.221 + 1G > A variant in AGK identified in the sister." (PMID 36253788, 2022). "They include Sengers syndrome (caused by a mutation in the AGK gene) and Barth syndrome (caused by a mutation in the TAZ gene)." (PMID 35611801, 2022). "AGK mutation is the leading cause of Sengers syndrome, characterized by congenital cataracts, hypertrophic cardiomyopathy, skeletal myopathy, lactic acidosis, and liver dysfunction." (PMID 35547757, 2022). "AGK mutations can alter both phospholipid metabolism and mitochondrial protein biogenesis, contributing to the pathogenesis of Sengers syndrome." (PMID 34948281, 2021). "Sengers syndrome (OMIM #212350) is a rare autosomal recessive disorder due to mutations in acylglycerol kinase (AGK) gene." (PMID 34164355, 2021). "The phenotype–genotype correlation reported in previous studies suggests that homozygous AGK nonsense variants result in a severe form of Sengers syndrome, while patients harboring splice site variants can survive the first decade of life." (PMID 34948281, 2021). "In this study, we sought to characterize the possible molecular mechanism underlying the pathogenicity of a novel homozygous AGK variant detected in a patient with suspected Sengers syndrome." (PMID 34948281, 2021).
Sengers syndrome (continued). "A clearer understanding of the manifold functions of AGK is essential to shed further light on the pathogenic mechanisms underlying Sengers syndrome." (PMID 34948281, 2021). "Sengers syndrome, an autosomal-recessive disorder manifested as hypertrophic cardiomyopathy, is due to mutation in acyl glycerol kinase (AGK)." (PMID 34360547, 2021). "Mutations in the AGK gene led to Sengers syndrome, an autosomal recessive mitochondrial disorder characterized by hypertrophic cardiomyopathy, congenital cataracts, skeletal myopathy, exercise intolerance, and lactic acidosis." (PMID 34651031, 2021). "Pathological variants in acylglycerol kinase (AGK) induce Senger syndrome, which is a rare recessive disorder characterized by lactic acidosis, hypertrophic cardiomyopathy, and bilateral cataracts." (PMID 33426505, 2020). "Sengers syndrome is caused by mutations in the gene encoding for mitochondrial acylglycerol kinase (AGK)." (PMID 33187128, 2020). "Recently, AGK, which had been implicated in Sengers syndrome, was identified as a component of the TIM22 complex." (PMID 30452684, 2018). "Mutations in another lipid related enzme, the acylglycerol kinase AGK, have been associated with hypertrophic cardiomyopathy, myopathy, cataracts, exercise intolerance and lactic acidosis (Sengers syndrome)." (PMID 31225486, 2018). "Alterations in body growth and muscle structure related to Sengers syndrome are in accordance with observed effects on body weight and weight gain in broilers with divergent alleles of the AGK c.1166 G > A polymorphism." (PMID 26552583, 2015). "Loss-of-function mutations of AGK in humans were shown to be causal for the occurrence of Sengers syndrome, suggestively based on dysfunction of mitochondrial lipid balance." (PMID 26552583, 2015). "We compare our findings to those in 21 previously reported AGK mutation-positive Sengers patients, confirming that Sengers syndrome is a clinically recognisable disorder of mitochondrial energy metabolism." (PMID 25208612, 2014). "Mutations in the acylglycerol kinase (AGK) gene have been recently described as the cause of Sengers syndrome in nine families." (PMID 25208612, 2014). "The infantile form of Sengers syndrome is caused by homozygous AGK nonsense mutations and is characterized by early onset (within the first few months of life) cardiomyopathy and lactic acidosis that causes death in infancy." (PMID 25208612, 2014). "Sengers syndrome is caused by mutations in the AGK gene, which is located on chromosome 7q34 and consists of 16 exons." (PMID 25208612, 2014). "Some patients who carry at least one AGK splice site variant or a start codon mutation develop a milder form of Sengers syndrome and have a markedly better prognosis." (PMID 25208612, 2014). "This study verifies the causative role of AGK in Sengers syndrome and expands the genotype-phenotype correlations of mutations in this gene." (PMID 25208612, 2014). "So far, all AGK mutations associated with Sengers syndrome are predicted to be loss-of-function variants." (PMID 25208612, 2014). "Recently, two nonsense mutations in the gene encoding the mitochondrial acylglycerol kinase (AGK) were identified from a patient with typical symptoms of Senger's syndrome." (PMID 23970947, 2013). "Sengers syndrome, characterized by hypertrophic cardiomyopathy, congenital cataracts, skeletal myopathy, exercise intolerance, and lactic acidosis, is caused by mutations in the AGK gene." (PMID 39817524, 2025). "Sengers syndrome (OMIM #212350) is a rare autosomal recessive disorder caused by mutations in the AGK gene and characterized by hypertrophic cardiomyopathy, congenital cataracts, and mitochondrial myopathy, including muscle weakness and lactic acidosis after exercise." (PMID 34948281, 2021).
Sengers syndrome (continued). "It has been shown that loss-of-function mutations in the AGK gene cause Sengers syndrome, an autosomal recessive mitochondrial disorder characterized by hypertrophic cardiomyopathy, congenital cataracts, skeletal myopathy, exercise intolerance, and lactic acidosis." (PMID 34651031, 2021). "Sengers syndrome is an autosomal recessive genetic disease caused by AGK mutations." (PMID 35237671, 2021). "The pathological mechanism underlying Sengers syndrome remains unclear, although it is thought to involve AGK’s role in lipid metabolism." (PMID 34948281, 2021). "Genetic testing of a boy revealed a homozygous pathogenic variant for Sengers syndrome in AGK (c.1131+2T>C) which was classified as likely pathogenic according to the ACMG guideline; besides, his skeletal muscle biopsy and transmission electron microscope presented obvious abnormity." (PMID 34164355, 2021). "Finally, exome sequencing revealed combined heterozygous stop variants in a gene called AGK in a patient with severe Sengers syndrome, and further biallelic AGK variants were identified in other patients with Sengers syndrome." (PMID 33179603, 2020). "In summary, we have identified six novel AGK mutations causing Sengers syndrome." (PMID 25208612, 2014). "Secondary to AGK mutations, a deficiency of the adenine nucleotide translocator and impairment of ATP synthesis has been reported and seems to play a central role in the pathomechanism of Sengers syndrome." (PMID 25208612, 2014). "However, we noted that homozygous AGK nonsense mutations have always resulted in infantile (severe) form of the Sengers syndrome while all patients who survived the first decade harbor at least one splice site variant or a start codon mutation." (PMID 25208612, 2014). "However, it remains to be determined whether the pathogenic mechanism underlying Sengers syndrome is due predominantly to loss of AGK lipid kinase activity or loss of AGK protein import activity, or indeed a combination of both." (PMID 34948281, 2021). "Physical examination and whole genome analysis revealed he was homozygous for an Icelandic founder mutation (p.Ile348AsnfsTer39) in the acylglycerol kinase (AGK) gene, and a diagnosis of Sengers syndrome was made based on symptoms and genotype." (PMID 36636586, 2023). "ANT1 levels were reduced in the cells of Sengers syndrome patients, suggesting that AGK is needed for the efficient insertion of metabolite carriers (e.g., SLC25A24 and ANT1)." (PMID 35237671, 2021). "Although some of the TIM22 patient’s symptoms may resemble those from Sengers syndrome patients, the molecular defects that we observed are solely associated with a carrier import deficiency and not with complementary lipid metabolism defects through loss of AGK." (PMID 30452684, 2018). "This moonlight function of AGK might explain the wide spectrum of mitochondrial abnormalities observed in Sengers syndrome." (PMID 36802007, 2023). "Evidence of a genotype–phenotype correlation in Sengers syndrome remains unclear, as the precise molecular function of AGK is yet to be elucidated." (PMID 34948281, 2021). "However, recent papers showed the role of AGK in mitochondrial protein import, which, on the other hand, does not answer the tissue-specific phenotype of biochemical abnormalities in Sengers syndrome." (PMID 33179603, 2020). "We also suggest that infants with cataract, even in the absence of cardiomyopathy, should be screened for Sengers syndrome or AGK mutations." (PMID 25208612, 2014). "Altogether, we report 8 new cases of Sengers syndrome with predicted loss-of-function mutations in all affected individuals with no hot-spot region in AGK gene." (PMID 25208612, 2014). "To date, only nine patients with AGK mutations have been reported to have a combined respiratory chain deficiency indicating that mtDNA depletion is not a common feature of Sengers syndrome." (PMID 25208612, 2014).
Sengers syndrome (continued). "It is believed that defects in lipid metabolism and/or mitochondrial carrier import due to the absence of functional AGK contribute to Sengers syndrome pathogenesis." (PMID 36475414, 2022). "Interestingly, and although AGK was not yet described as a component of the TIM22 complex, decreased levels of Adenine nucleotide transporter 1 (a metabolite carrier) were reported for Sengers syndrome patients." (PMID 34356047, 2021).
breast carcinoma (11 papers, 2014 to 2025). "Acylglycerol Kinase (AGK), a lipid kinase, has been found to be aberrantly expressed in breast cancer and is closely associated with tumor proliferation, migration, and invasion." (PMID 39594764, 2024). "In summary, our results have demonstrated that AGK plays an important role in human breast cancer progression and have provided insights into the underlying mechanisms." (PMID 24886245, 2014). "Combined with our observation that upregulation of AGK was implicated in the proliferation and tumorigenicity of breast cancer cells both in vivo and in vitro." (PMID 24886245, 2014). "Evaluating the molecular diagnostic ability of AGK in breast cancer is merited." (PMID 24886245, 2014). "Although AGK has been shown to be overexpressed in several types of cancer and has been associated with cancer progression and development, its clinical significance and biological role in human breast cancer remains unclear." (PMID 24886245, 2014). "Furthermore, overexpression of AGK enhanced G1-S phase transition in breast cancer cells, which was associated with activation of AKT, suppression of FOXO1 transactivity, downregulation of cyclin-dependent kinase inhibitors p21Cip1 and p27Kip1 and upregulation of the cell cycle regulator cyclin D1." (PMID 24886245, 2014). "This study demonstrates that Netupitant effectively inhibits the proliferation of breast cancer cells by targeting AGK." (PMID 39594764, 2024). "The results indicated that AGK gene expression is critical for both subtypes of breast cancer cells, underscoring its potential as a broad-spectrum therapeutic target for breast cancer treatment." (PMID 39594764, 2024). "Firstly, the role of AGK in the metastasis of breast cancer and the potential of Netupitant to inhibit the migration and invasion of triple-negative breast cancer cells remain unexplored." (PMID 39594764, 2024). "Netupitant inhibits the activation of the PI3K/AKT/mTOR signaling pathway by suppressing the AGK protein, inducing the apoptosis of breast cancer cells." (PMID 39594764, 2024). "Among these, Netupitant at a concentration of 40 μmol/L exhibited strong inhibitory effects on both cell lines, suggesting its potential to target AGK and inhibit breast cancer progression, warranting further investigation." (PMID 39594764, 2024). "In breast cancer, AGK enhances tumorigenesis and cellular proliferation by inhibiting the transcription factor FOXO1." (PMID 39594764, 2024). "Several previous studies provided evidences that the expression of AGK is upregulated in breast cancer, kidney cancer and nasopharyngeal cancer." (PMID 35934718, 2022). "A previous study reported that AGK can suppress FOXO1 transcriptional activity in breast cancer cells 27, similar to our study." (PMID 35910796, 2022). "For example, AGK expression induces breast cancer cell proliferation and enhances the G1‐S phase transition." (PMID 32827244, 2020). "Acylglycerol kinase was reported to promote the growth of cells and tumorigenicity in breast cancer by inhibiting the expression of FOXO1.TIMP3 is a versatile extracellular regulator in cancers." (PMID 29796115, 2018). "MTT and colony formation assays showed that overexpression of AGK increased the proliferation of breast cancer cells, whereas silencing AGK drastically reduced cell proliferation." (PMID 26443540, 2016). "AGK expression in breast cancer cell lines, paired patient tissues were determined using immunoblotting and Real-time PCR." (PMID 24886245, 2014). "Kaplan-Meier survival curves and log-rank test showed that AGK expression was significantly correlated with overall survival (OS) in breast cancer (P < 0.001)." (PMID 24886245, 2014). "Functional assays, such as colony formation, anchorage-independent growth and BrdU assay, and a xenograft tumor model were used to determine the oncogenic role of AGK in human breast cancer progression." (PMID 24886245, 2014).